SNTG2 (syntrophin gamma 2)
Description:
Adapter protein that binds to and probably organizes the subcellular localization of a variety of proteins. May link various receptors to the actin cytoskeleton and the dystrophin glycoprotein complex (By similarity).
Synonyms: G2SYN; SYN5
Tractability: Antibody: its Gene Ontology location is reachable by antibodies, with high confidence; UniProt places it where antibodies can reach, with medium confidence; the Human Protein Atlas places it where antibodies can reach. PROTAC: ubiquitination databases record sites on it.
Gene: Protein-coding gene on chromosome 2 (950,849 to 1,367,613, forward strand). Ensembl gene ENSG00000172554.
Subcellular location: Cell membrane, sarcolemma; Cytoplasm, cytoskeleton
Subcellular location (Human Protein Atlas): Plasma membrane; Nucleoplasm
Pathways (Reactome):
Extracellular matrix organization: Formation of the dystrophin-glycoprotein complex (DGC)
Gene Ontology:
Molecular function: neuroligin family protein binding; PDZ domain binding; protein binding; structural molecule activity
Biological process: central nervous system development
Cellular component: plasma membrane; dystrophin-associated glycoprotein complex; syntrophin complex; cytoskeleton; sarcolemma
Genetic constraint (gnomAD): Loss-of-function variants: 67 observed, 65.38 expected, observed/expected ratio (o/e) 1.02, 90% interval 0.84 to 1.26. The upper end of that interval is the gene's LOEUF score, 1.26, which puts it in group 5 of 6, group 1 being the genes least tolerant of losing a copy. Missense variants: 669 observed, 653.3 expected, observed/expected ratio (o/e) 1.02, 90% interval 0.96 to 1.09. Synonymous variants: 258 observed, 256.76 expected, observed/expected ratio (o/e) 1, 90% interval 0.91 to 1.11.
Homologues: Orthologues: chimpanzee SNTG2 (99% identical), macaque SNTG2 (89% identical), rat Sntg2 (83% identical), mouse Sntg2 (83% identical), tropical clawed frog SNTG2 (73% identical), dog SNTG2 (70% identical), zebrafish sntg2 (64% identical), Drosophila melanogaster Syn2 (36% identical), Caenorhabditis elegans stn-2 (31% identical). Paralogues in human: SNTG1 (49% identical), SNTA1 (27% identical), SNTB1 (25% identical), SNTB2 (24% identical).
Diseases named in the same sentence as SNTG2 in open-access papers:
SNTG2 is named in the same sentence as 14 diseases in open-access papers, as found by Europe PMC text mining. Sharing a sentence is not in itself a finding about the gene and the disease. The quoted sentences say what the papers report.
autism (5 papers, 2012 to 2024). Persistent deficits in social interaction and communication and interaction as well as a markedly restricted repertoire of activity and interest as well as repetitive patterns of behavior. "The SNTG2 gene is expressed in various tissues in humans and was reported to be associated with osteoporotic vertebral fracture and autism." (PMID 34209805, 2021). "SNTG2 binds to neuroligins 3 and 4, genes that have been associated with autism, and known autism-related mutations in those neuroligins weaken the binding with SNTG2." (PMID 24988487, 2014). "For example, a mutation in the PDZ protein, NLGNX, perturbed its PDZ domain interaction with the ligand protein, SNTG2, which is suggested to be a cause of mental retardation and autism." (PMID 22346764, 2012). "In particular, it was observed that the binding of neuroligins to SNTG2, at inhibitory synapses can be influenced by mutations in neuroligins, showing how interactions between neuroligins and SNTG2 could be implicated in the aetiology of autism." (PMID 38674362, 2024). "We also identified PSGs associated with communication disorders, such as autism (CNTNAP4, AHI1, FAN1, SNTG2, and GRIP1) and dyslexia (KIAA0319)." (PMID 33441416, 2021). "Furthermore, the PSGs expressed in the brain and under the highest positive selection include CNTNAP4, FAN1, SNTG2, and KIAA0319, which also display high levels of expression in the cerebellum and have been associated with communication disorders, such as autism and dyslexia." (PMID 33441416, 2021).
schizophrenia (2 papers, 2012 to 2021). A major psychotic disorder characterized by abnormalities in the perception or expression of reality. "Alterations of SNTG2 and MYT1L have been previously reported in patients with ASD and schizophrenia, respectively." (PMID 22346768, 2012).
osteoporosis (1 paper, 2020). A condition of reduced bone mass, with decreased cortical thickness and a decrease in the number and size of the trabeculae of cancellous bone (but normal chemical composition), resulting in increased fracture incidence. "In addition, the study of these molecules SNTG2, TRAF3IP2, and ITGA6 can be tested as therapeutic targets in osteoporosis‐related VF." (PMID 32602654, 2020).
SNTG2 also shares sentences with these, for which no sentence is quoted: neurodevelopmental disorder (2 papers); Alzheimer disease (1); asthma (1); benign meningioma (1); cancer (1); communication disorder (1); dyslexia (1); infection (1); meningioma (1); Parkinson disease (1); viral infection (1).